SUCLA2 (succinate-CoA ligase ADP-forming subunit beta)
Description:
ATP-specific succinyl-CoA synthetase functions in the citric acid cycle (TCA), coupling the hydrolysis of succinyl-CoA to the synthesis of ATP and thus represents the only step of substrate-level phosphorylation in the TCA. The beta subunit provides nucleotide specificity of the enzyme and binds the substrate succinate, while the binding sites for coenzyme A and phosphate are found in the alpha subunit (By similarity). Also able to act as an ATP-specific itaconyl- and malyl-CoA synthetase.
Synonyms: A-SCS; SCS-betaA; A-BETA; LINC00444; MTDPS5
Tractability: PROTAC: ubiquitination databases record sites on it; its protein half-life has been measured; a small molecule that binds it is known.
Target class: Enzyme; Ligase
Safety:
Unwanted effects reported when the protein is acted on. In parentheses: how it was acted on, where the effect was seen, and who reports it.
thiopurine-induced myelosuppression (source: ClinPGx)
thiopurine-related cytopenia (source: ClinPGx)
Gene: Protein-coding gene on chromosome 13 (47,745,736 to 48,037,968, reverse strand). Ensembl gene ENSG00000136143.
Subcellular location: Mitochondrion
Subcellular location (Human Protein Atlas): Mitochondria
Pathways (Reactome):
Metabolism: Citric acid cycle (TCA cycle)
Gene Ontology:
Molecular function: acid-thiol ligase activity; malate-CoA ligase activity; protein binding; succinate-CoA ligase (ADP-forming) activity; ATP binding; catalytic activity; magnesium ion binding; metal ion binding
Biological process: malate metabolic process; toxic metabolite repair; succinyl-CoA catabolic process; succinyl-CoA metabolic process; succinyl-CoA pathway; tricarboxylic acid cycle; succinate metabolic process
Cellular component: catalytic complex; extracellular exosome; mitochondrion; mitochondrial matrix; succinate-CoA ligase complex; succinate-CoA ligase complex (ADP-forming)
Genetic constraint (gnomAD): Loss-of-function variants: 30 observed, 57.07 expected, observed/expected ratio (o/e) 0.53, 90% interval 0.39 to 0.71. The upper end of that interval is the gene's LOEUF score, 0.71, which puts it in group 2 of 6, group 1 being the genes least tolerant of losing a copy. Missense variants: 476 observed, 580.65 expected, observed/expected ratio (o/e) 0.82, 90% interval 0.76 to 0.88. Synonymous variants: 172 observed, 196.77 expected, observed/expected ratio (o/e) 0.87, 90% interval 0.77 to 0.99.
Gene-disease validity (ClinGen):
ClinGen rates the evidence that SUCLA2 causes each of these diseases.
Leigh syndrome (autosomal recessive): Definitive. A progressive neurological disease defined by specific neuropathological features associating brainstem and basal ganglia lesions.
mitochondrial disease (autosomal recessive): Definitive.
Homologues: Orthologues: chimpanzee SUCLA2 (99% identical), macaque SUCLA2 (97% identical), rabbit SUCLA2 (96% identical), guinea pig SUCLA2 (93% identical), mouse Sucla2 (91% identical), dog SUCLA2 (87% identical), pig SUCLA2 (87% identical), rat Sucla2 (86% identical), tropical clawed frog sucla2 (80% identical), zebrafish sucla2 (79% identical), Caenorhabditis elegans suca-1 (57% identical), Drosophila melanogaster ScsbetaA (56% identical). Paralogues in human: SUCLG2 (48% identical).